DPP3 (dipeptidyl peptidase 3)
Description:
Cleaves and degrades bioactive peptides, including angiotensin, Leu-enkephalin and Met-enkephalin. Also cleaves Arg-Arg-beta-naphthylamide (in vitro).
Synonyms: DPPIII
Tractability: Small molecule: it has a binding pocket of medium quality. PROTAC: ubiquitination databases record sites on it; its protein half-life has been measured.
Target class: Metallo protease; Metallo protease M49 family; Protease; Metallo protease MAE clan; Enzyme
Gene: Protein-coding gene on chromosome 11 (66,479,990 to 66,510,188, forward strand). Ensembl gene ENSG00000254986.
Subcellular location: Cytoplasm, cytosol
Subcellular location (Human Protein Atlas): Cytosol
Pathways (Reactome):
Cellular responses to stimuli: KEAP1-NFE2L2 pathway
Metabolism of proteins: Neddylation
Gene Ontology:
Molecular function: dipeptidyl-peptidase activity; protein binding; zinc ion binding; metalloexopeptidase activity
Biological process: proteolysis
Cellular component: cytosol; extracellular exosome; cytoplasm
Genetic constraint (gnomAD): Loss-of-function variants: 59 observed, 88.64 expected, observed/expected ratio (o/e) 0.67, 90% interval 0.54 to 0.83. The upper end of that interval is the gene's LOEUF score, 0.83, which puts it in group 3 of 6, group 1 being the genes least tolerant of losing a copy. Missense variants: 794 observed, 954.13 expected, observed/expected ratio (o/e) 0.83, 90% interval 0.78 to 0.88. Synonymous variants: 361 observed, 398.43 expected, observed/expected ratio (o/e) 0.91, 90% interval 0.83 to 0.99.
Homologues: Orthologues: chimpanzee DPP3 (99% identical), macaque DPP3 (99% identical), pig DPP3 (96% identical), rabbit DPP3 (94% identical), rat Dpp3l1 (94% identical), guinea pig DPP3 (93% identical), dog DPP3 (93% identical), mouse Dpp3 (93% identical), zebrafish dpp3 (68% identical), tropical clawed frog dpp3 (67% identical), Caenorhabditis elegans dpt-1 (48% identical), Drosophila melanogaster DppIII (48% identical).
Diseases named in the same sentence as DPP3 in open-access papers:
DPP3 is named in the same sentence as 51 diseases in open-access papers, as found by Europe PMC text mining. Sharing a sentence is not in itself a finding about the gene and the disease. The quoted sentences say what the papers report.
Sepsis (20 papers, 2020 to 2025). Sepsis is defined as life-threatening organ dysfunction caused by a dysregulated host response to infection. "With regard to patients with sepsis, DPP3 levels on admission were significantly associated with the hepatic and coagulation SOFA subscores on day 2, and to a lesser extent with renal and neurological dysfunction." (PMID 40572747, 2025). "In the AdrenOSS-1 study, DPP3 levels were significantly associated with 28-day mortality in ICU patients with sepsis or septic shock." (PMID 40572747, 2025). "High concentrations of circulating DPP3 (cDPP3) have been associated with worse outcomes during sepsis." (PMID 38849640, 2024). "Just recently, Mebazaa and coworkers have associated high DPP3 levels in critically ill patients with sepsis and cardiogenic shock with reduced cardiac output and low left ventricular function, a high SOFA and liver SOFA score, and short-term mortality." (PMID 32796765, 2020). "Furthermore, it was demonstrated that the DPP3 plasma levels are associated with the survival rate of patients suffering from sepsis, cardiogenic shock, heart failure, and acute kidney injury." (PMID 32546481, 2020). "Interestingly, preclinical animal studies demonstrated that intravenous injection of DPP3 in healthy rodents caused impairment of cardiac function, while cDPP3 inhibition with a specific monoclonal antibody restored cardiac function in a rodent sepsis model." (PMID 36530868, 2022). "It was thus concluded that DPP3 levels not only increase in septic patients compared to healthy subjects, but also reflect the severity of sepsis, since they tend to be significantly higher in patients with septic shock compared to patients with severe sepsis." (PMID 40572747, 2025). "In vitro and animal studies were excluded from the search, since our goal was to provide an overview of the clinical utility of bio-ADM and DPP3 in patients with sepsis or septic shock." (PMID 40572747, 2025). "Bio-ADM and DPP3 have shown promising results as novel hypoperfusion biomarkers in patients presenting to the ED or the ICU with sepsis or septic shock." (PMID 40572747, 2025). "On the other hand, DPP3 appears to be useful mainly for sepsis prognosis and for predicting sepsis-induced acute kidney injury." (PMID 40572747, 2025). "It was found that both groups of patients with severe sepsis and septic shock exhibited significantly higher levels of DPP3 compared to healthy participants." (PMID 40572747, 2025). "The detection of such a signal in DARK-Sepsis would justify the use of renin or DPP3 as biomarkers to enrich the study population of a large clinical efficacy trial of AT2 in septic shock." (PMID 38475822, 2024). "In rodent models, inhibition of DPP3 via a monoclonal antibody was shown to restore cardiac function in sepsis and improve haemodynamics in heart failure." (PMID 37733154, 2023). "Previous studies have shown that circulating concentrations of both DPP3 and ADM are independently associated with the development of organ failure and adverse outcome in sepsis." (PMID 33381880, 2021). "Recently, both ADM‐enhancing therapies aimed at improving endothelial barrier function and vascular tone and DPP3‐blocking therapies aimed at restoring systemic angiotensin responses have been shown to improve outcome in various preclinical sepsis models." (PMID 33381880, 2021). "Circulating DPP3 alone was a moderate predictor of 30-day mortality with AUROCs of 0.68, 0.62, and 0.72 in the entire group, the sepsis subgroup, and the cardiac arrest subgroup, respectively." (PMID 34429159, 2021). "Both ADM‐enhancing therapies aimed at improving endothelial barrier function and DPP3‐blocking therapies aimed at restoring systemic angiotensin responses have been shown to improve outcome in various preclinical sepsis models." (PMID 33381880, 2021).
Sepsis (continued). "In sepsis, elevated plasma DPP3 promotes excessive degradation of angiotensin II into angiotensin IV, while leaving angiotensin I unaffected—thereby increasing the angiotensin I/II ratio and reducing AT1 receptor stimulation, a mechanism that contributes to circulatory collapse." (PMID 41226854, 2025). "Furthermore, DPP3 levels were significantly higher in patients with septic shock than in patients with severe sepsis." (PMID 40572747, 2025). "Considering that AST, ALT and LDH reached their peak values at least two days later than DPP3, the latter finding could imply that DPP3 may serve as an early marker of cellular damage during the initial phases of critical illness, including sepsis." (PMID 40572747, 2025). "Notably, significantly higher DPP3 baseline levels were observed in patients with septic shock (29.1 [18–48.2] ng/mL) compared to patients with severe sepsis (23.2 [15.2–35.1] ng/mL)." (PMID 40572747, 2025). "Indeed, increased plasma DPP3 levels have been reported in critically ill patients with sepsis, septic shock, cardiogenic shock and burn-induced vasodilatory shock." (PMID 40572747, 2025). "In the AdrenOSS-1 study, it was shown that serial measurements of DPP3 levels in ICU patients during the early phase of sepsis could predict organ dysfunction." (PMID 40572747, 2025). "Likewise, DPP3 levels have been found to be elevated in animal models of septic shock and in human patients with sepsis, especially those with high severity of illness or those who ultimately die." (PMID 38475822, 2024). "Notably, in animal models of sepsis, DPP3 inhibition improves hemodynamics and survival by mitigating septic cardiomyopathy, an effect potentially mediated by the resulting increase in AT2 levels." (PMID 38475822, 2024). "Collectively, these data suggest that renin and DPP3 warrant additional prospective study as biomarkers in sepsis and specifically as biomarkers that may identify patients likely to benefit from AT2 therapy." (PMID 38475822, 2024). "Finally, though additional human data are needed to evaluate this theory, the use of pharmacologic AT2 has been suggested as an option to combat the hemodynamic deterioration induced by elevated DPP3 in sepsis." (PMID 38475822, 2024). "So far, DPP3 has been described as a biomarker in sepsis, indicating severity and mortality." (PMID 37733154, 2023). "Although observational, this study first provided the first suggestion that bio-ADM and DPP3 might represent two distinct and partly independent pathophysiological mechanisms involved in the development of organ dysfunction during sepsis." (PMID 36530868, 2022). "Furthermore, administration of the same DPP3 antibody in murine sepsis attenuated sepsis‐induced cardiac dysfunction and improved overall survival." (PMID 33381880, 2021). "No study investigated the potential diagnostic role of DPP3 in sepsis." (PMID 40572747, 2025). "The ratio of ACE to DPP3 was strikingly inverted between controls and septic patients (<0.1), suggesting that excess DPP3 may contribute to impaired angiotensin II responses in sepsis." (PMID 41226854, 2025). "Renin and dipeptidyl peptidase 3 (DPP3) are components of the renin–angiotensin–aldosterone system which have been shown to outperform lactate in predicting sepsis prognosis, and preliminary data suggest they could prove useful as biomarkers to guide AT2 use in septic shock." (PMID 38475822, 2024). "The aim of this narrative review is to provide insight into the role of two novel biomarkers, namely adrenomedullin (ADM) and dipeptidyl peptidase 3 (DPP3), in sepsis." (PMID 40572747, 2025). "It is evident that DPP3 and bio-ADM represent two different biological pathways along the course of sepsis which contribute to the development of septic shock and subsequent organ dysfunction." (PMID 40572747, 2025).
Sepsis (continued). "In this review, we focus on dipeptidyl peptidase 3 (DPP3) and adrenomedullin (ADM), two molecules that act on the vasculature and are involved in the pathophysiology of sepsis and septic shock." (PMID 33381880, 2021). "Given the availability of rapid bedside biomarker assays for both DPP3 and ADM, they represent promising opportunities for the conduct of biomarker‐guided sepsis trials." (PMID 33381880, 2021). "Instead, increased ACE2 and DPP3 expression were observed, with serum DPP3 higher in both normal- and high-renin sepsis groups compared to controls." (PMID 41226854, 2025). "Among several candidate biomarkers of sepsis that have emerged in recent years, this review provides existing evidence on the potential clinical utility of two novel biomarkers, adrenomedullin in its bio-active form (bio-ADM) and dipeptidyl peptidase 3 (DPP3)." (PMID 40572747, 2025). "Finally, procizumab, a monoclonal antibody designed to inhibit circulating DPP3 activity in order to limit the degradation of peptides of the RAS, has been tested in a preclinical model of sepsis induced by CLP." (PMID 37986086, 2023). "Several pathophysiological hypotheses could explain these results, including reduced ACE activity, as shown in experimental sepsis or pediatric septic shock or increased degradation of Ang II, either by ACE2 or by peptidases, such as circulating dipeptidyl peptidase 3 (cDPP3)." (PMID 40126750, 2025).
breast carcinoma (13 papers, 2013 to 2025). "The levels of a series of essential fatty acids, such as oleic acid (FFA(18:1)), linoleic acid (FFA(18:2)), gamma-linolenic acid, palmitoleic acid (FFA(16:1)) and arachidic acid (FFA(20:0)), are significantly reduced in DPP3-deficient breast cancer cells." (PMID 38655619, 2024). "This study demonstrates that DPP3 plays a role in the reprogramming of fatty acid metabolism in tumors and is associated with poor prognosis in breast cancer patients." (PMID 38655619, 2024). "In this study, we found that DPP3 over-expression is highly associated with shortened survival time in breast cancer patients." (PMID 38655619, 2024). "In addition, multivariate analysis indicated that “treatment” and “tumor stage” were significantly associated with high-risk factors, while DPP3 expression levels were an independent survival determinant in breast cancer patients." (PMID 34359286, 2021). "In addition, our results showed that DPP3 might be a potential target in the treatment of breast cancer, but the underlying molecular mechanism still needs to be further studied." (PMID 38655619, 2024). "Collectively, these results revealed the effect of DPP3 on the proliferation, invasion, migration, apoptosis and autophagy of breast cancer cells." (PMID 38655619, 2024). "Based on the analysis of the distribution of DPP3 expression among clinicopathological features of breast cancer, upregulation of DPP3 is more common in patients with distant metastasis." (PMID 38655619, 2024). "We conducted a series ofin vitro cell biology assays to explore the biological function and mechanisms of DPP3 in breast cancer." (PMID 38655619, 2024). "Kaplan-Meier curve analysis showed upregulation of DPP3 consistently correlates with significantly shorter overall survival in breast cancer patients (P<0.0001)." (PMID 38655619, 2024). "In MCF-7 human breast cancer cells, the binding of DPP3 with KEAP1 stabilizes KEAP1, thereby allowing Nrf-2 to accumulate and locate in the nucleus and affect prognosis through the regulation of apoptosis." (PMID 38655619, 2024). "Among the seven members of the DPP family, DPP3 exhibits the most significant difference in expression between the tumor-to-normal stage based on the breast cancer transcriptomic profile from the TCGA database." (PMID 38655619, 2024). "The high expression of DPP3 in breast cancer indicates poor prognosisin silico; however, its specific role and molecular mechanisms are still not well known." (PMID 38655619, 2024). "Our study suggested that DPP3 is also highly correlated with poor prognosis in breast cancer patients." (PMID 38655619, 2024). "First, this study was mainly carried out using breast cancer cell lines, and further studies are needed to investigate the effect of the DPP3/FASN axis on breast cancer progressionin vivo." (PMID 38655619, 2024). "Our study focused on the role of the DPP3 protein in breast cancer.DPP3 KO in breast cancer cells can significantly inhibit the growth and migration of tumor cells and induce apoptosis." (PMID 38655619, 2024). "DPP3 expresses at a higher level in breast cancer tissues than that in adjacent tissues in both TCGA database and clinical samples." (PMID 38655619, 2024). "Consistently, the DPP3 protein level is significantly higher in breast cancer tissues than in normal controls based on analysis of the CPTAC database." (PMID 38655619, 2024). "Several reports on DPP3 have suggested its aberrant activity in cancers of multiple origins, such as breast cancer, lung cancer, ovarian cancer, endometrial cancer, colon cancer, and EC." (PMID 37531267, 2023). "In breast cancer, it was shown that DPP3 expression during oxidative stress induction leads to up-regulation of the NRF2 pathway." (PMID 37531267, 2023). "In breast cancer, DPP3 was shown to be overexpressed and elevated levels of DPP3 mRNA correlated with increased NRF2 downstream gene expression and poor prognosis." (PMID 37531267, 2023).
breast carcinoma (continued). "The other Keap1-Nrf2 disruptor dipeptidyl-peptidase 3 (DPP3) is over-expressed in estrogen receptor-positive breast cancer leading to poor prognosis." (PMID 35126099, 2021). "Here, MCF-7 ER (+) breast cancer cells were used to demonstrate that the DPP3 interaction with KEAP1 was dose-dependently reinforced by increasing the amount of oxidative stressors." (PMID 33805996, 2021). "High expression levels of DPP3 and DPP4 were associated with poor survival of breast cancer patients, whereas high expression levels of DPP6, DPP7, DPP8, and DPP9 were associated with good prognoses." (PMID 34359286, 2021). "This evidence was consistent with our data, as we found that DPP3 had high expression levels in breast cancer tissues at both the transcription and protein levels, and further caused poor prognoses in breast cancer patients." (PMID 34359286, 2021). "The oxidative stress-mediated dipeptidyl-peptidase 3 (DPP3) -KEAP1 interaction enhanced the function of NRF2 to promote breast cancer cell survival." (PMID 33292585, 2020). "Luet al. found that DPP3 could support breast cancer cell survival by stabilizing the expressions of other proteins." (PMID 38655619, 2024). "Additionally, DPP3 protein and mRNA were highly expressed in breast cancer tissues compared with those in adjacent breast tissues." (PMID 38655619, 2024). "In this study, the expression of DPP3 in breast cancer tissues is analyzed using TCGA database." (PMID 38655619, 2024). "After the role of DPP3 in the regulation of NRF2 pathway activation in breast cancer was described in detail, it was speculated that it might also serve as a therapeutic target in other NRF2-driven malignancies." (PMID 37531267, 2023). "Importantly, overexpression and aberrant activity of DPP3 have been reported in several malignancies, including ovarian cancer, breast cancer, lung cancer, and cervical cancer." (PMID 37531267, 2023). "Collectively, DPP family members, especially DPP3, may serve as essential prognostic biomarkers in breast cancer." (PMID 34359286, 2021). "Finally, by analyzing the data from the TCGA database, DPP3 was found to be overexpressed in human breast cancer and to correlate with increased NRF2 target gene expression and poor prognosis, especially in ER (+) breast cancer." (PMID 33805996, 2021). "Interestingly, we observed that LSM4 was closely ranked with other breast cancer biomarkers, such as DPP3, CDK5, and TRIB3." (PMID 34638387, 2021). "Based on our results, DPP3 might be a novel prognostic biomarker for breast cancer." (PMID 38655619, 2024). "Through its interaction with fatty acid synthetase (FASN), DPP3 can stabilize FASN, induce the synthesis of fatty acids and thus promote the development of breast cancer." (PMID 38655619, 2024). "Western blot analysis of human breast cancer samples also showed that DPP3 and FASN were more highly expressed in breast cancer tissues than in normal tissues." (PMID 38655619, 2024). "The results showed that DPP3 and DPP9 had significantly high expression profiles in breast cancer tissues relative to normal breast tissues." (PMID 34359286, 2021). "Results from an Oncomine analysis showed that mRNA expression levels of DPP3 and DPP9 were highly upregulated in breast cancer tissues, whereas DPP4, DPP6, and DPP8 exhibited downregulated levels in breast cancer tissues relative to normal breast tissues." (PMID 34359286, 2021). "DPP3 and DPP9 mRNA expression levels were upregulated in breast cancer tissues relative to normal breast tissues and other subtypes." (PMID 34359286, 2021). "Similarly, the protein dipeptidyl peptidase 3 (DPP3) was shown to inhibit NRF2 ubiquitination through binding to KEAP1, thus activating NRF2-dependent gene transcription in breast cancer." (PMID 33808001, 2021).